NFATC2 (nuclear factor of activated T cells 2)
Diseases named in the same sentence as NFATC2 in open-access papers (continued):
Sharing a sentence is not in itself a finding about the gene and the disease.
colon carcinoma (13 papers, 2011 to 2023). "In patients with colon cancer, tumor expression of nuclear NFATc1 was associated with inferior survival while tumor expression of NFATc2 correlated with superior survival." (PMID 26795951, 2016). "For example, NFATc1 promotes proliferation of hepatocellular carcinoma cells, NFATc2 increases the invasiveness of breast cancer cells, and NFATc3 and NFATc4 promote the progression of colon cancer." (PMID 28881766, 2017). "In patients with colon cancer, tumor expression of NFATc2 correlated with superior survival, while nuclear NFATc1 with inferior survival." (PMID 26795951, 2016). "To determine if these laboratory observations provide clinical insight, we investigated the relationship of NFATc1 and NFATc2 tumor expression and the survival of patients with history of colon cancer." (PMID 26795951, 2016). "Besides driving the transcription of tumor-promoting genes such as c-Myc and cyclin-dependent kinase-6 (CDK6), a previous study explored a critical oncogenic role of NFATc2 in colitis-induced colon cancer by control of proinflammatory cytokine IL-6 production." (PMID 32041943, 2020). "Both NFATc2 and NFAT5 promote the migration and invasion of breast and colon cancer cells." (PMID 28235034, 2017). "NFATc2 likely opposes the action of NFATc1, NFATc3, and NFATc4 in colon cancer cells as those tumors lacking NFATc2 expression most likely had a more aggressive clinical course driven in part by the unopposed actions of NFATc1, NFATc3, and NFATc4." (PMID 26795951, 2016).
colorectal cancer (13 papers, 2014 to 2025). A primary or metastatic malignant neoplasm that affects the colon or rectum. "It was also reported on experimental model of colitis-associated colorectal carcinoma, that NFATC2-deficient mice were protected from tumor development and show significantly reduced levels of the downstream critical proinflammatory cytokines interleukin IL21 and IL6." (PMID 24416320, 2014). "In addition, some studies have also disclosed that Zfp90 played a critical role in initiating colitis-associated colorectal cancer through modulating the nuclear factor of stimulated T-cells and the cytoplasmic 2 (NFATC-2)/bone morphogenic protein-4 (BMP-4) pathway." (PMID 36900383, 2023). "Recent studies have demonstrated that NFATC2 promotes the stemness of colorectal cancer stem cells via AJUBA-mediated YAP activation and constitutes a novel therapeutic target." (PMID 37601778, 2023). "NFATC2 regulates the self-renewal capacity and tumorigenic initiation of tumor stem cells and is a promising therapeutic target for colorectal cancer treatment." (PMID 37628631, 2023). "For instance, NFATc2 promoted cancer stemness of colorectal cancer via AJUBA-mediated YAP activation." (PMID 36077186, 2022). "NFATC2 is involved in many mechanisms including inflammation, apoptosis, and colorectal cancer." (PMID 38304289, 2023).
glioma (12 papers, 2013 to 2026). A benign or malignant brain and spinal cord tumor that arises from glial cells (astrocytes, oligodendrocytes, ependymal cells). "So it appears that NFATC2 controls the cell cycle distribution of glioma U251 cells by helping more cells move into the mitosis phase, causing a big increase in how fast glioma cells can grow because of this." (PMID 41578162, 2026). "And it is also put forth that NFATC2 takes part in regulating the growth of glioma cells by way of MRPS16, Statistical significance was assessed using Student's t‐test." (PMID 41578162, 2026). "The Wnt/β—Catenin/NFATC2 pathway plays a role in promoting glioma cell proliferation by MRPS16, which is shown in our experimental data." (PMID 41578162, 2026). "To verify NFATC2 as the mediator for MRPS16's regulation over glioma cell proliferation, we conducted OE experiments with regard to NFATC2 accompanied by MRPS16 knockdown." (PMID 41578162, 2026). "Through further prediction and gene transformation of cultured cells, it is confirmed that the presence of MRPS16 promotes the proliferation of glioma cells through the Wnt/β‐catenin/NFATC2 pathway." (PMID 41578162, 2026). "By comparison, we have made it clear that MRPS16 regulates the proliferation of glioma cells through the increased expression of NFATC2." (PMID 41578162, 2026). "MRPS16 and NFATC2 promote glioma cell proliferation, which was confirmed by in vivo BALB/c mice inoculation." (PMID 41578162, 2026). "All glioma cells showed high levels of NFATc3, while NFATc1 and NFATc2 expression levels were variable among the cells." (PMID 34443374, 2021). "Microarray analysis demonstrated that NFATc2 was overexpressed in glioblastoma when compared to low-grade gliomas, and the expression of the NFATc2 protein in U87 and U251 glioblastoma cells has been linked to their increased invasiveness." (PMID 34443374, 2021). "MRPS16 can promote glioma tumour proliferation and inhibit glioma cell apoptosis, so it might be supposed that MRPS16 could control the multiplication of glioma cells by way of the way in which Wnt/β—Catenin/NFATC2." (PMID 41578162, 2026). "Overall, MRPS16 and NFATC2 were shown to promote glioma cell proliferation in BABL/c mice." (PMID 41578162, 2026). "Glioma cells proliferating induced by MRPS16 may involve Wnt/β − Catenin/NFATC2 signaling pathway." (PMID 41578162, 2026). "Furthermore, it is also possible that the effect of Wnt/β—Catenin/NFATC2 signalling pathway on glioma cell proliferation may occur through MRPS16." (PMID 41578162, 2026). "NFATC2 has a variety of regulatory functions, but its role in glioma cells has not been reported before." (PMID 41578162, 2026). "Unlike in the immune cells with dominant expression of NFATc2, NFATc3 in glioma cells could still interact with calcineurin through an alternative binding site and remain activated despite blocking of the PxIxIT docking site by 11R-VIVIT." (PMID 34443374, 2021).
cardiac hypertrophy (11 papers, 2014 to 2025). "SIRT2 can bind to the Nuclear Factor of Activated T Cells 2(NFATc2) and deacetylate it, further repressing the occurrence of pathological cardiac hypertrophy." (PMID 39226168, 2024). "Cardiac-specific activation of the calcineurin-NFAT pathway was sufficient to induce myocardial hypertrophy, whereas both pharmacological inhibition and genetic deletion of NFATc2 and c3 alleviated pathological remodeling in animal models." (PMID 34089101, 2021). "SIRT2 can bind to NFATc2 and deacetylate it, inhibit NFATc2’s activity and then inhibit this signal transduction pathway and inhibit the occurrence of pathological myocardial hypertrophy." (PMID 34028177, 2021). "Bourajjaj M. et all, 2008, have shown that NFATC2 is a necessary mediator of calcineurin-dependent cardiac hypertrophy and heart failure." (PMID 24479926, 2014). "In addition to regulating AMPK pathway, Sirt2 can also deacetylate NFATc2 and inhibit the pathological of myocardial hypertrophy." (PMID 40523615, 2025). "Furthermore, deletion of NFATc2 gene has been shown to significantly inhibit pressure overload-induced heart hypertrophy." (PMID 27746739, 2016). "For example, the hypomethylation of NFATc2 is predicted to activate RCAN1 and NPPB, which are related to exercise-induced cardiac hypertrophy and concentric hypertrophic cardiomyopathy, respectively." (PMID 38793603, 2024). "SIRT2 was reported to repress cardiac hypertrophy via diverse mechanisms, including activation of AMPK and repression of GSK3b and NFATc2." (PMID 33611744, 2021). "For example, the pharmacological NFATc3 inhibitor A-285222 protected from endothelial dysfunction in a murine diabetes model but does not block NFATc2 playing a central role in pathological myocardial hypertrophy." (PMID 34089101, 2021). "We observed no further alterations in NFATc2 at AB1–18 weeks, and a persistent decrease in NFATc3 mRNA throughout cardiac hypertrophy and dilatation." (PMID 39086965, 2022).
glioblastoma (10 papers, 2013 to 2025). The most malignant astrocytic tumor (WHO grade IV). "In fact, NFATc2 has been shown in prior work to be particularly important in regulating glioblastoma invasion." (PMID 25889879, 2015). "Similarly, miR-454-3p exerts tumor-suppressive functions by down-regulation of NFATc2 in glioblastoma." (PMID 34016788, 2021).
Burkitt lymphoma (8 papers, 2006 to 2022). A rare form of malignant mature B-cell non-Hodgkin lymphoma. "Antigen receptor-driven apoptosis of transformed B cells (Burkitt lymphoma) also has been shown to be a consequence of Nfatc2-mediated signals, suggesting loss of Nfatc2 could provide a survival advantage to malignant B cells." (PMID 24945807, 2014). "Knock-down of IRF4 in a T1 LCL (infected with the Zp-V3-containing Akata strain) induced lytic reactivation whereas over-expression of IRF4 in Burkitt lymphoma cells inhibited both NFATc1 and NFATc2 expression and lytic EBV reactivation." (PMID 35472072, 2022). "Consistently, active NFATC1 and NFATC2 can induce lytic EBV gene expression in EBV positive Burkitt lymphoma cells." (PMID 36383217, 2022). "Further studies demonstrated that NFATC2 suppresses neoplastic changes in chondrogenesis and displays pro-apoptotic activity in Burkitt lymphoma." (PMID 25057852, 2014). "Under the same conditions Nfatc2−/− B cells were found to be resistant to apoptosis induction supporting earlier work on the pro-apoptotic role of NFATc2 in BCR-mediated apoptosis in human Burkitt ́s lymphoma B cells." (PMID 22764736, 2012). "Furthermore, we find that IRF4 over-expression decreases the levels of both NFATc1 and NFATc2 in EBV-positive Burkitt lymphoma cells and inhibits lytic EBV reactivation in response to BCR activation." (PMID 35472072, 2022). "Furthermore, while NFATc1 inhibits the ability of BCR activation to induce apoptosis in Burkitt lymphoma cells, NFATc2 has the opposite effect." (PMID 32059024, 2020). "Nevertheless, we cannot exclude the possibility that EBNA2 type-dependent regulation of NFATc1/NFATc2 expression is specific to LCLs and not present in the context of Burkitt lymphoma cells." (PMID 32059024, 2020).
gastric cancer (8 papers, 2016 to 2024). A primary or metastatic malignant neoplasm involving the stomach. "Inhibiting the STAT3/MSK1/NFATc2 axis, including calcium blockers, can substantially decrease the proliferation and growth of gastric cancer cells in xenograft models." (PMID 39309860, 2024). "The interaction between STAT3 and MSK1 at the NFATc2 promoter drives H3S10 phosphorylation-dependent transcription, which in turn activates inflammatory pathways associated with gastric cancer genesis." (PMID 39309860, 2024). "Collectively, these results support a notion that STAT3/MSK1/NFATc2 form a functional axis in carcinogen-induced gastric tumor development, and provide potential therapeutic targets for human gastric cancer." (PMID 32041943, 2020). "Accordingly, in MNU-induced mice gastric tumors and human clinical gastric cancer tissues, we observed increased expression of NFATc2 and IL-6 in tumor cells, indicating an autocrine pathway was activated in tumorigenesis." (PMID 32041943, 2020). "Inhibiting the STAT3/MSK1/NFATc2 signaling axis significantly suppressed gastric cancer cell proliferation and xenograft tumor growth, which provides a potential novel approach for gastric carcinogenesis intervention by regulating aberrant epigenetic and transcriptional mechanisms." (PMID 32041943, 2020). "The amplificated CNV of immune‐related genes in gastric cancer tissues was accompanied by the increase of their mRNA level (e.g., LRRN3 and NFATC2), and vice versa (e.g., MAGEC1)." (PMID 34582114, 2022). "In gastric cancer (GC), the transient receptor potential canonical 3 (TRPC3) promotes tumorigenesis via the CNB2/GSK3β/NFATc2 signaling pathway; thus, TRPC3 could be a possible target for therapeutic intervention." (PMID 39822413, 2024).
lung carcinoma (8 papers, 2013 to 2022). "In the literature, only one research group has reported NFATc2 expression in 52% of 159 lung cancers and similar to our findings, high expression was associated with late tumor stage and poor survival." (PMID 28737489, 2017). "For functional studies, NFATc2 was silenced by 2 shRNA sequences (shNFATc2-A and -B) in 2 lung cancer cell lines with high basal expression (HCC827, PDCL#24), and ectopically expressed in 2 cell lines with relatively low de novo expression (A549, H1299)." (PMID 28737489, 2017). "Nevertheless, the findings implicate NFATc2 is a potential therapeutic target for sequential or combination therapy of lung cancer that aims to eliminate TIC." (PMID 28737489, 2017). "Our data reveal a novel mechanism of SOX2 upregulation in lung cancers through enhancer binding by NFATc2." (PMID 28737489, 2017). "Using H441 lung cancer cell line with NFATc2 transient overexpression, we observed only sites 1, 4 and 5 showed statistically significant increased reporter activities while those of sites 4 and 5 were reciprocally abolished by CSA treatment." (PMID 28737489, 2017). "In human lung cancers, high NFATc2 expression predicted poor tumor differentiation, adverse recurrence-free and cancer-specific overall survivals." (PMID 28737489, 2017). "The high expression of the Ca2+ pathway transcription factor NFATc2 is considered to be a new regulator for lung cancer to initiate cell phenotype, and high NFATc2 expression predicted poor tumor differentiation, adverse recurrence-free, and cancer-specific overall survivals in human lung cancers." (PMID 34497656, 2021). "Together, the data strongly supported NFATc2/SOX2/ALDH1A1 form a regulatory axis in lung cancer." (PMID 28737489, 2017). "Indeed, SOX2 expression is significantly correlated with that of NFATc2 in this group of human lung cancer." (PMID 28737489, 2017). "In the longer-term, combining classic cancer treatments with new therapeutic strategies targeting NFATc2 could make treatments for lung cancer patients more effective." (PMID 28737489, 2017). "The clinical significance of NFATc2/SOX2 coupling was further assessed in human lung cancers." (PMID 28737489, 2017). "Similarly, NFATc2 overexpression increased cisplatin resistance in a lung cancer cell line." (PMID 31040921, 2019). "The results showed that TICs had higher levels of the NFATc2 protein than other lung cancer cells that were not TICs." (PMID 28737489, 2017). "On the other hand, we have shown NFATc1 inhibition does not result in SOX2 suppression, indicating NFATc2 is likely to be preferentially involved in lung cancers." (PMID 28737489, 2017). "In this study, using NFATc2 depletion and overexpression models of multiple lung cancer cell lines in TIC-defining functional assays, as well as clinical evidence from excised human lung cancers, we showed NFATc2 mediates TIC phenotypes." (PMID 28737489, 2017). "Until now, however, it was not known if NFATc2 is also important in TICs in lung cancer." (PMID 28737489, 2017). "Furthermore, TIC selected by the lung TIC markers ALDH+/CD44+ from HCC827 and the patient-derived lung cancer cell lines, HKUCL2 and HKUCL4, showed higher NFATc2 expression than the ALDH-/CD44- non-TIC counterpart." (PMID 28737489, 2017).
diabetes (7 papers, 2016 to 2025). "Our results showing that trans-eQTL linkages of the GWAS candidate genes to the Nfatc2 locus in mouse is consistent with NFATC2 association with diabetes traits in humans." (PMID 27935966, 2016). "TRPC6 knockout in type 2 diabetes mellitus induced hepatic inflammation and fibrosis, inhibited calcium overload, and suppressed the calcineurin/nuclear factor of activated T cells 2/NLRP3 signaling pathway in mice." (PMID 41450741, 2025). "Using LocusZoom, a visualization tool of publically-available GWAS data, we asked if SNPs near human NFATC2 and NFATC1 genes are associated with diabetes-related phenotypes." (PMID 27935966, 2016). "Among these, NFATC2, which prefers the C allele of the rs3811792 polymorphic SCD5 promoter, was confirmed by several predictive programs, and this polymorphism was also shown to modify the promoter activity and to be associated with diabetes." (PMID 36292669, 2022).
osteoarthritis (7 papers, 2018 to 2025). A noninflammatory degenerative joint disease occurring chiefly in older persons, characterized by degeneration of the articular cartilage, hypertrophy of bone at the margins and changes in the synovial membrane. "For instance, mice overexpressing NFAT1 demonstrate osteoporosis and a reduction in bone volume, while germline deletion of Nfatc2 has been associated with osteoarthritis." (PMID 40119681, 2025). "The transcription factor NFAT1 (also called NFATC2,) which was initially identified as a repressor of the immune response, could be involved in the pathogenesis of osteoarthritis." (PMID 36733912, 2023).
colitis (6 papers, 2012 to 2023). Inflammation of the colon. "In fact, NFATc1 and c2 deficient mice display impaired Th1 and Th2 response, and NFATc2 deficiency has been reported to suppress colitis induced by oxazolone administration." (PMID 22479554, 2012). "Moreover, NFATc2 deficiency suppresses CD4+ T cell-mediated colitis in mice." (PMID 33251043, 2020). "Calcineurin inhibitors, that target NFATc2 also appear to be effective in patients with CPI colitis." (PMID 37872166, 2023). "Here, we found much more nuclear localization of NFATc2 in colon-infiltrated cells of Trpv1G564S+/+ mice with colitis." (PMID 33251043, 2020). "NFATC2 is involved in colitis by controlling mucosal T cell activation in an IL-6-dependent manner and seems to be a potential therapeutic target for UC." (PMID 31249629, 2019). "Thus, we speculated that TRPV1 gain of function exacerbates DSS-induced colitis, at least in part, through promoting NFATc2 activation in DCs." (PMID 33251043, 2020). "We also investigated whether the calcineurin/NFATc2 cascade was altered in the colitis model." (PMID 33251043, 2020). "One of the key transcriptional regulators predicted to activate the gene expression changes observed in polyfunctional mucosal lymphocytes was NFATc2, which is also highly upregulated in the colon of patients with CPI colitis." (PMID 37872166, 2023).
lupus (5 papers, 2014 to 2025). "To further confirm the inhibitory effect of HCQ on NFATc2 nuclear translocation, we performed immunocytochemistry analysis in purified lupus CD4+ T cells." (PMID 28793932, 2017). "We first confirmed the up-regulation of CaN and NFATc2 in lupus Tfh in public dataset GSE157648." (PMID 40989817, 2025).
lymphoma (5 papers, 2017 to 2024). A malignant (clonal) proliferation of B- lymphocytes or T- lymphocytes which involves the lymph nodes, bone marrow and/or extranodal sites. "On the other hand, NFATc2 is implicated in an inhibitory effect on tumorigenesis, including induction of cell cycle arrest and apoptosis; thus, spontaneous lymphoma development was observed in NFATc2-deficient mice." (PMID 33800389, 2021). "Differentially regulated genes were enriched for classical lymphoma driver genes downstream of the BCR, including MALT1 and CARD11, as well as NFATC2, TNFRSF13C (BAFF), and components of the NF-κB (RELB, IRAK1, BCL3, and TNFRSF1B) pathway." (PMID 39082968, 2024).
viral infection (5 papers, 2016 to 2024). "Interestingly, NFATc1 and NFATc2 deficient OTI cells were able to control the virus infection as efficiently as WT OTI cells." (PMID 38346075, 2024). "Following acute virus infection, the total CD8+ and CD4+ T cell response remained unaffected by the absence of NFATc1 or NFATc2 in the spleen or lymph nodes at 7 dpi." (PMID 38346075, 2024).